LEP (leptin)
Diseases named in the same sentence as LEP in open-access papers (continued):
Sharing a sentence is not in itself a finding about the gene and the disease.
breast cancer (continued). "Similarly, a study was done to find out how leptin might impact the activity of breast cancer stem cells (BCSCs) using patient-derived samples." (PMID 38202341, 2023). "To test this hypothesis, we conducted a meta-analysis on genetic alterations in LEP and ADIPOQ genes as well as their receptor-encoded genes by pooling published summary data, aiming to evaluate their association with risk for breast cancer, as well as circulating leptin and adiponectin levels." (PMID 37274250, 2023). "Interestingly, elevated cAMP may inhibit leptin-induced migration of highly aggressive breast cancer cells MDA-MB-231 by suppressing ERK1/2 and STAT3 signaling pathway." (PMID 36755926, 2023). "In addition, CAAs can also secrete chemokine ligand 2 (CCL2), chemokine ligand 5 (CCL5), and interleukin-1β (IL-1β), Interleukin-6 (IL-6), tumor necrosis factor-α (TNF-α), vascular endothelial growth factor (VEGF) and leptin, which can promote the invasion and metastasis of breast cancer." (PMID 37305043, 2023). "Thus, the use of antibodies targeting leptin/Ob-R able to perform an antagonist activity could be used in breast cancer therapy." (PMID 36835413, 2023). "In addition, studies have reported the relationship between Leptin and post-chemotherapy fatigue in breast cancer, where the expression of Leptin increases during fatigue, and the results suggest that Leptin is a potential biomarker for post-chemotherapy fatigue." (PMID 37542585, 2023). "Moreover, NLRP3 inflammasome activation by leptin supplementation induced breast cancer growth." (PMID 36794014, 2023). "In summary, our study suggests that high levels of CRP, leptin and leptin-to-adiponectin ratio could lower breast cancer risk among premenopausal women but not among postmenopausal women." (PMID 35430795, 2022). "The combination of soluble breast adipocyte-derived leptin, insulin, IL-6, and TNF-α were inducers of the release of angiogenic mediators in macrophages, representing a potential mechanism for the enhanced risk of breast cancer progression in obese individuals." (PMID 35701840, 2022). "After adjustment for BMI, associations between leptin, adiponectin and leptin/adiponectin ratio and breast cancer risk were no longer significant, while a significant positive association was observed for IL-6 (ORper SD increment = 1.32 (1.12–1.55); ORQ4vsQ1 = 1.55 (1.04–2.30), P-trend = 0.01)." (PMID 35948877, 2022). "The results are consistent with in vitro findings related to adipose-derived stem cells (ASCs) and their production of adipsin and leptin as part of fat-related abnormal proteins that could explain their different abilities to promote the growth of breast cancer tumor cells from surgical specimens." (PMID 35627631, 2022). "Moreover, in obese breast cancer patients, leptin levels were significantly increased in the tumor microenvironment compared to circulating plasma samples, suggesting an important role for this adipokine as an active player in tumor microenvironment communication." (PMID 36361728, 2022). "We performed a nested case-control study to examine whether pre-diagnostic circulating concentrations of adiponectin, leptin, c-reactive protein (CRP), tumour necrosis factor-α, interferon-γ and 6 interleukins were associated with breast cancer risk, overall and by menopausal status." (PMID 35430795, 2022). "The high ratio of serum leptin/adiponectin might indicate the presence of aggressive breast cancer." (PMID 35701840, 2022). "Specifically, leptin significantly increased PBX3 mRNA expression by enhancing the activity of the PBX3 promoter in a STAT3‐dependent manner in breast cancer (BC) cells." (PMID 35068042, 2022). "Furthermore, it has been reported that LEP in breast cancer models, via JAK2/STAT3 pathway, promotes cell cycle progression by increasing the expression of cdk2 and cyclin D1 levels, thus inducing hyperphosphorylation and subsequent inactivation of the cell cycle inhibitor Rb." (PMID 36291602, 2022).
breast cancer (continued). "Since we reported a strong inverse association between BMI and breast cancer in this population, the negative association between leptin and breast cancer may result from residual confounding." (PMID 35948877, 2022). "Furthermore, the ratio between leptin/ObR serum levels (Free Leptin Index—FLI) is considered a useful predictor of leptin activity, reflecting the individual metabolic status and when increased it is an important risk factor for breast cancer development." (PMID 33644151, 2021). "However, other studies of SNPs in EB7H3 have identified associations with C-reactive protein (CRP) levels and plasma leptin levels in women, soluble leptin receptor levels, E. histolytica infection in children, luminal A breast cancer, tolerance for exercise intensity, and exercise participation." (PMID 34421692, 2021). "In addition, higher circulating E2 were poor prognostic factor but leptin may be a protection signal in elderly postmenopausal Chinese patients with breast cancer." (PMID 34970222, 2021). "However, DP relationships with adipokines (i.e., adiponectin and leptin) among breast cancer survivors remain unclear." (PMID 34684340, 2021). "However, our data shows that leptin can have differential effects on the induction of autophagy in different breast cancer cells and we suggest that different effects might be due to the cancer cell mutational background." (PMID 33763424, 2021). "Moreover, when co-injecting MCF7 breast cancer cells and transfected MSCs with leptin shRNA into SCID/beige mice, a reduction in leptin levels in MSCs occurs, finally causing a decrease in the number of metastatic lesions and in the MCF7 tumor volume in the mouse livers and lungs." (PMID 33472580, 2021). "It has also been found that leptin induces the expression of aromatase genes by affecting PKC/MAPK signaling, which ultimately leads to an increase in the estrogen expression level, increasing the risk of breast cancer and promoting the development of breast cancer." (PMID 34485124, 2021). "In addition to promoting breast cancer growth through stimulation of proliferation, leptin may also inhibit apoptosis of breast cancer cells by downregulating pro-apoptotic genes." (PMID 33859943, 2021). "Indeed, our results revealed that elevated serum leptin levels occur in an advanced stage of the disease, being significantly associated with tumor ulceration (p = 0.0005) and shorter DFS (p = 0.0217), as reported for women with breast cancer." (PMID 33644151, 2021). "Thus, to investigate whether leptin affects cancer cell‐specific metabolism, we first examined the effect of leptin on ATP production in breast cancer cells." (PMID 33226729, 2021). "Interestingly, the higher serum ObR levels were found in cats with mammary carcinomas presenting a HER2-positive/ER-negative status (p = 0.0291), as reported for human breast cancer patients, confirming the crosstalk between the leptin/ObR axis and the EGFR downstream signaling pathway." (PMID 33644151, 2021). "However, in a recent study, we demonstrated that the fasting-mediated enhancement of endocrine therapy activity in hormone receptor-positive breast cancer (HR+ breast cancer) also relies on the ability of fasting to blunt circulating insulin and leptin concentrations." (PMID 34439167, 2021). "Furthermore, taking into account potential off‐target effects of fatostatin as previously reported, the role of SREBP‐1 was further confirmed by gene silencing of SREBP‐1, allowing to conclude that SREBP‐1‐mediated lipogenesis is required for FAO stimulation by leptin in breast cancer cells." (PMID 33226729, 2021). "We hypothesized that the leptin–Ob-R axis in breast cancer is involved in activating T cells." (PMID 34868066, 2021).
breast cancer (continued). "Indeed, cats with luminal B or HER2-positive mammary carcinoma showed significantly lower serum leptin levels when compared with controls (p < 0.001 and p < 0.05, respectively), revealing that serum leptin levels are downregulated in tumors with PR-positive status and/or HER2-positive status." (PMID 33644151, 2021). "Altogether, our results support the hypothesis that serum levels of leptin and ObR can be used as biomarkers of specific feline mammary carcinoma subtypes, and suggests the use of leptin antagonists as a therapeutic tool, reinforcing the utility of the cat as a cancer model." (PMID 33644151, 2021). "In summary, LEP may play a role in breast carcinoma development." (PMID 34414945, 2021). "In addition, our previous study indicated that leptin was expressed at much higher levels in adipocytes than 3T3-L1 preadipocytes, and the crosstalk between adipocytes and breast cancer cells constituted a feedback system to sustain high levels of leptin in the coculture system." (PMID 33371368, 2020). "Therefore, the diminution of adiponectin (an anti-inflammatory adipokine) and exacerbation of leptin and YKL-40 (pro-inflammatory cytokines) in normal-weight breast cancer subjects may be associated with a more aggressive tumour phenotype." (PMID 32512860, 2020). "Furthermore, leptin treatment increases HER2 protein levels in breast cancer cells." (PMID 33046976, 2020). "Furthermore, we found that the circulating FSH level was significantly associated with higher adiponectin levels, but not with leptin in relatively healthy postmenopausal women without breast cancer, after adjusting for age, BMI, and menopause duration." (PMID 33086618, 2020). "Using as experimental models MCF-7 breast cancer cells surviving long-term treatment with the AI anastrozole (AnaR) and Ana-sensitive counterparts, we found that AnaR cells expressed higher levels of leptin and its receptors (ObR) along with a constitutive activation of downstream effectors." (PMID 32260113, 2020). "Also, higher leptin/adiponectin ratio may induce breast cancer growth, as well as hyperinsulinemia and elevated levels of insulin-like growth factor 1 (IGF-1)." (PMID 31720917, 2020). "Additionally, leptin promoted migration and invasion of breast cancer cells." (PMID 32836215, 2020). "Also, the high circulating leptin concentration could counteract cisplatin-induced cytotoxicity in breast cancer cells." (PMID 33511131, 2020). "Accordingly, inhibition of the leptin signaling pathway by using a specific peptide significantly reduced the growth and motility of AnaR breast cancer cells, highlighting the existence of an autocrine feedback loop that sustains the more aggressive behavior of AI resistant breast cancer cells." (PMID 32260113, 2020). "However, although several studies support the crucial involvement of leptin in breast cancer, definitive conclusions on the biological significance of ObR in breast cancer epithelial cells and on its role in mediating tumor/stroma crosstalk deserve further investigation." (PMID 32727138, 2020). "In addition to its effect on breast cancer growth, leptin may also play an important role in bone metastasis." (PMID 32033341, 2020). "Leptin and its receptors have been reported to have roles in many physiological events mostly related to food intake, energy consumption, hemostasis, ovulation, fertilization, angiogenesis, obesity and breast cancer in a variety of species including mice and humans." (PMID 32133259, 2020). "Thus, leptin induced the EMT phenotype in breast cancer cells." (PMID 32836215, 2020). "Leptin signaling may lead to STAT3 activation of HIF-1α in breast cancer and therefore may also drive CPT1 expression resulting in nuclear regulation of energy generation; a critical activity for cellular survival particularly in unfavourable hypoxic environments." (PMID 32331320, 2020). "Our results therefore suggest that leptin might be an effective target in breast cancer therapy." (PMID 32836215, 2020).
breast cancer (continued). "The concentration of the secreted exosomes in the conditioned medium of leptin-treated cells was significantly higher compared to the number of exosomes seeded from control cells, suggesting that leptin treatment might increase the ability of breast cancer cells to release exosomes." (PMID 31336913, 2019). "To unravel the possible molecular mechanism by which leptin may modulate exosome formation in breast cancer cells, we performed time course study to evaluate the effects of leptin on the expression of the main proteins involved in exosome biogenesis and secretion processes." (PMID 31336913, 2019). "Importantly, leptin induces the expression of Twist and β-catenin in breast cancer cells." (PMID 31554180, 2019). "One strength of this study was the use of a longitudinal study design with repeated measurements of outcomes at various time points, which allowed us to determine whether a decrease in leptin levels signalled a rise in the fatigue experienced by breast cancer patients at a separate time point." (PMID 31016867, 2019). "Moreover, we did not observe any significant changes in the expression of proteins belonging to the Rab family of small GTPase, involved in MVB mobilization and fusion to plasma membrane, further highlighting Tsg101 as a leptin effector in breast cancer able to control exosome biogenesis." (PMID 31336913, 2019). "These evidences are in line with the role of leptin in promoting growth and invasion of breast cancer that could be additionally sustained through the induction of Tsg101 expression, since Tsg101 plays an important role in several aspects of breast tumor progression." (PMID 31336913, 2019). "In our study, the relationship between leptin and breast cancer risk differed depending on age; increased plasma leptin levels were significantly associated with decreased breast cancer risk in younger participants (<51 years old) but not older participants (≥51 years old)." (PMID 31292496, 2019). "Accordingly, we found in breast cancer cells that the member of the Hsp family Hsp90, which we have previously demonstrated to be a leptin target gene, physically interacts with Tsg101 in basal condition and that the amount of Tsg101 bound to Hsp90 results enriched in cells treated with leptin." (PMID 31336913, 2019). "Indeed, leptin has been shown to have several pro-tumorigenic effects, including increased cell proliferation, transformation, antiapoptotic effects, self-renewal and reduced efficacy of breast cancer treatments." (PMID 30634494, 2019). "Interestingly, women with breast cancer present high levels of leptin and of its receptor ObR." (PMID 30404206, 2018). "Therefore, we speculated that coculture activates leptin expression in MDA-MB-231 breast cancer cells, forming a feedback loop." (PMID 30563531, 2018). "Interestingly, the LEP G2548A polymorphism is related to variations in the levels of leptin in serum; however, this polymorphism was not related to the susceptibility to develop breast cancer." (PMID 30404206, 2018). "In the present study, we demonstrated that leptin promotes the growth of ER-positive breast cancer cells but does not significantly affect ER-negative breast cancer cells, suggesting that ER signaling is involved in leptin-induced growth of breast cancer cells." (PMID 29312618, 2017). "On the other hand, it is impossible to extrapolate the results obtained from leptin stimulation in the cell lines with the results of expression that could be obtained directly from obese patients with breast cancer due to the complexity of the metabolic environment of the tumor in vivo." (PMID 29311755, 2017). "Furthermore, leptin intervenes estrogen effects on malignant tissue via a paracrine pathway, as well as enhances other influences that participate in cell growth and angiogenesis during breast cancer development." (PMID 29121911, 2017).
breast cancer (continued). "Therefore, aiming for either leptin or signaling mediated by leptin receptor might eliminate BCSCs or even avert recurrences and metastasis completely in breast cancer patients." (PMID 28970834, 2017). "Therefore, inhibition of leptin–cytokine cross-talk might serve as a preventative or adjuvant measure to target breast cancer, particularly in obese women." (PMID 28270795, 2017). "Importantly, leptin was shown to upregulate VEGF in breast cancer via HIF-1 and NFκB; thus it could confer an additional advantage to tumors under hypoxic conditions." (PMID 28915700, 2017). "Given their opposing impact on breast cancer risk, some have proposed that the adiponectin: leptin ratio, rather than levels of individual adipokines, may be more informative for evaluating breast cancer risk profile." (PMID 27338371, 2016). "However, our experiments in vivo showed that depleting mouse macrophages and neutralizing mouse IL-8 significantly reduced leptin-induced xenograft growth and metastasis, which clearly support that macrophage-derived IL-8 can contribute to leptin-induced breast cancer progression." (PMID 27588409, 2016). "Thus, targeting specific CAFs-secreted factors, such as leptin, may provide more effective treatment options to achieve therapeutic benefits in breast cancer patients." (PMID 26899873, 2016). "Thus, leptin may induce the release of cancer-promoting factors from M2 macrophages to indirectly stimulate breast cancer progression." (PMID 27588409, 2016). "Thus, elevation of the leptin-ObR-IL-8 axis in breast cancer may actually reflect cancer progression." (PMID 27588409, 2016). "Interestingly, leptin increased mammosphere formation in metastatic breast cancers and expression of OBR as well as HSP90, a target of leptin signaling, were directly correlated with mammosphere formation in metastatic samples (r = 0.68/p = 0.05; r = 0.71/p = 0.036, respectively)." (PMID 26556856, 2016). "Moreover, the FXR ligand induces a decrease on leptin-mediated up-regulation of its own gene (Ob) expression, highlighting how this nuclear receptor is able to negatively interfere in the short autocrine loop maintained by leptin on Ob gene in breast cancer cells." (PMID 26899873, 2016). "The critical role played by leptin in mammary tumourigenesis has generated a great interest in the design and development of several leptin signalling modulators that could interfere with the action of leptin and thereby prevent or delay breast cancer development and progression." (PMID 25721149, 2015). "There is accumulating evidence that leptin signalling might be involved in the development of several types of cancer, such as colon cancer, mammary cancer, prostate cancer, and epithelial ovarian cancer, as well as the development of several myeloid and lymphoid leukemic cell lines." (PMID 26508818, 2015). "Furthermore, to determine whether leptin secreted by obASCs alone enhances breast cancer cell proliferation, CM from lnASCs and obASCs treated with leptin neutralizing antibody were exposed to BCCs." (PMID 26286584, 2015). "Leptin can stimulate the growth of cancer cells through expression of aromatase and production and activation of estrogen in breast cancer epithelium, resulting in reduction or inhibition of inhibitory effects of antiestrogens in proliferation of breast cancer cells." (PMID 26199932, 2015). "Since adiponectin and leptin have been reported to have opposing activities on breast cancer progression, we also assessed whether their ratio might provide an index of intervention effectiveness but found that the variability of the ratio makes it problematic in this regard." (PMID 26132992, 2015). "In addition, it has been reported that leptin may induce breast cancer to undergo a transition from epithelial to spindle-like mesenchymal morphology, activating the signaling pathways devoted to the EMT." (PMID 25505738, 2014).